ILRUN (inflammation and lipid regulator with UBA-like and NBR1-like domains)
Description:
Negative regulator of innate antiviral response. Blocks IRF3-dependent cytokine production such as IFNA, IFNB and TNF. Interacts with IRF3 and inhibits IRF3 recruitment to type I IFN promoter sequences while also reducing nuclear levels of the coactivators EP300 and CREBBP.
Synonyms: C6orf106; FLJ22195; dJ391O22.4; FP852
Tractability: PROTAC: ubiquitination databases record sites on it.
Gene: Protein-coding gene on chromosome 6 (34,587,288 to 34,696,881, reverse strand). Ensembl gene ENSG00000196821.
Subcellular location: Cytoplasm; Nucleus
Subcellular location (Human Protein Atlas): Nuclear speckles; Centrosome; Cytosol
Gene Ontology:
Molecular function: protein binding; ubiquitin binding
Biological process: negative regulation of defense response to virus; negative regulation of DNA binding; negative regulation of protein localization to nucleus; negative regulation of tumor necrosis factor production; negative regulation of type I interferon production; macroautophagy
Cellular component: cytoplasm; cytosol; nuclear speck; nucleus; phagophore assembly site
Genetic constraint (gnomAD): Loss-of-function variants: 2 observed, 33.52 expected, observed/expected ratio (o/e) 0.0597, 90% interval 0.023 to 0.19. The upper end of that interval is the gene's LOEUF score, 0.19, which puts it in group 1 of 6, group 1 being the genes least tolerant of losing a copy. Missense variants: 205 observed, 382.58 expected, observed/expected ratio (o/e) 0.54, 90% interval 0.48 to 0.6. Synonymous variants: 122 observed, 143.8 expected, observed/expected ratio (o/e) 0.85, 90% interval 0.73 to 0.99.
Homologues: Orthologues: chimpanzee ILRUN (100% identical), dog ILRUN (97% identical), rat Ilrun (96% identical), mouse Ilrun (95% identical), macaque ILRUN (94% identical), zebrafish ilrun (78% identical), guinea pig ILRUN (76% identical), tropical clawed frog ilrun (75% identical), pig ILRUN (72% identical).
Diseases named in the same sentence as ILRUN in open-access papers:
ILRUN is named in the same sentence as 7 diseases in open-access papers, as found by Europe PMC text mining. Sharing a sentence is not in itself a finding about the gene and the disease. The quoted sentences say what the papers report.
Obesity (3 papers, 2021 to 2025). Accumulation of substantial excess body fat. "We find UHRF1BP1 and ILRUN mediate the effect of obesity on CAD whereas methylation sites within NOS3 and CKM mediate the effect of their associated-risk factors on CAD." (PMID 33574266, 2021). "It has been suggested that the impact of ILRUN on lipids and obesity may be via its transcription regulatory effect on components of RAAS." (PMID 37274792, 2023). "POC5, ILRUN, FDFT1, and NEIL2 mediated the impact of CpG sites on obesity through metabolic pathways." (PMID 37274792, 2023). "Integration of methylation data with gene expression profiles revealed putative mediators of these relationships—genes such as ILRUN, POC5, FDFT1, NEIL2, and others—whose methylation changes may affect metabolic pathways and contribute to obesity pathogenesis." (PMID 41303351, 2025).
COVID-19 (2 papers, 2023 to 2025). A disease caused by infection with severe acute respiratory syndrome coronavirus 2. "The results of these genetic factors in the genes (TLR7, UNC13D, DES, SPEG, LZTFL1, ABO, ILRUN, and CACFD1) provide substantial insights into the genesis of cardiovascular issues linked with COVID-19." (PMID 40002898, 2025). "The SNP (rs10490770) located near LZTFL1 suggested direct causality (SNPs → COVID-19 → CHD), and SNPs in ABO (rs579459, rs495828), ILRUN(rs2744961), and CACFD1(rs4962153, rs3094379) may simultaneously influence COVID-19 severity and CHD risks." (PMID 37964352, 2023). "Shared genetic variants contributed to the causality, where rs10490770 in LZTFL1 suggested direct causality (SNPs → COVID-19 → CHD), and SNPs in ABO (rs579459, rs495828), ILRUN (rs2744961), and CACFD1(rs4962153, rs3094379) may simultaneously influence their risks." (PMID 37964352, 2023).
coronary artery disease (1 paper, 2025). "The molecular features of ILRUN were shown to be associated with several diseases and disorders, including cancer, coronary artery disease, obesity, and viral infections." (PMID 40002898, 2025).
ILRUN also shares sentences with these, for which no sentence is quoted: Autoimmunity (1 paper); fibromyalgia (1); metabolic syndrome (1); type 2 diabetes mellitus (1).